Y_RNA (Y RNA )
Gene: Miscellaneous RNA gene on chromosome 1 (161,699,506 to 161,699,607, forward strand). Ensembl gene ENSG00000199595.
Homologues: Orthologues: chimpanzee Y_RNA (98% identical). Paralogues in human: RNY3 (88% identical), Y_RNA (87% identical), Y_RNA (86% identical), RNY3P1 (85% identical), Y_RNA (85% identical), Y_RNA (84% identical), Y_RNA (83% identical), RNY3P14 (82% identical), Y_RNA (82% identical), RNY3P16 (81% identical), Y_RNA (81% identical), RNY3P11 (80% identical), and 95 more.